IL33 (interleukin 33)
Diseases named in the same sentence as IL33 in open-access papers (continued):
Sharing a sentence is not in itself a finding about the gene and the disease.
myeloproliferative neoplasm (9 papers, 2015 to 2025). A clonal hematopoietic stem cell disorder, characterized by proliferation in the bone marrow of one or more of the myeloid (i.e., granulocytic, erythroid, megakaryocytic, and mast cell) lineages. "In our AML models (MLL-AF9 and DNMT3A/FLT3ITD), as was seen in myeloproliferative neoplasm models, the main source of IL-33 is stromal cells." (PMID 40691440, 2025). "Regarding BCR-ABL1-positive myeloproliferative neoplasms, CD34+ cells from CML patients were targeted by IL-33." (PMID 31652497, 2019). "On the other hand, it is worth mentioning that the IL-33/ST2 signaling has been reported to contribute to CML progenitor growth and the pathogenesis of myeloproliferative neoplasms, but lacked assessment of host immune responses." (PMID 27517629, 2016).
preeclampsia (9 papers, 2011 to 2025). Preeclampsia is a hypertensive disorder of pregnancy that is characterized by new-onset hypertension with proteinuria presenting after 20 weeks of gestation, and depending on mild or severe forms may initially present with severe headache, visual disturbances, and hyperreflexia. "IL-33 has been associated with miscarriage, preterm labor, and preeclampsia, the last of which has been associated with IL-33 and ST2 during the sixth week of gestation." (PMID 39065188, 2024). "Pre-eclampsia is a disease caused by placental derived factors, and we show that IL-33 and ST2 can be detected in lysates from both normal and pre-eclampsia placentas." (PMID 21949719, 2011). "The authors noted that a reduction in IL-33 production may lead to a proinflammatory state, inducing placental insufficiency linked to preeclampsia development." (PMID 39171751, 2024). "A protective role for IL-33 in pregnancy has been suggested, as lower serum concentrations of IL-33 in patients with preeclampsia were observed, along with an inverse correlation to BMI." (PMID 39171751, 2024). "Accordingly, low levels of IL-33 and/or high levels of sST2 were shown in the serum or placental tissue of preeclampsia patients (26‐32), while both IL-33 and sST2 concentrations have been increased in the serum of gestational diabetes patients." (PMID 37972259, 2023). "Numerous studies have shown that IL-33 had an essential role in pregnancy-related diseases such as recurrent abortion and preeclampsia." (PMID 35998104, 2022). "Available tools—such as biomarker measurement (troponins, ST2/IL-33, telomere length) or the identification of obstetric histories, including preeclampsia or gestational diabetes—enable the early detection of elevated CVR and the initiation of timely interventions to prevent adverse outcomes." (PMID 41226915, 2025). "Since we observed a significant increase in both IL-33 and sST2 in patients with RSA, this phenomenon may be due to the maternal immune system’s response to preeclampsia." (PMID 35095557, 2021).
prostate carcinoma (9 papers, 2016 to 2025). A carcinoma that arises from epithelial cells of the prostate gland. "In order to prove that, future mulitvariant analysis will be required to evaluate IL-33 mRNA/protein expression levels with clinicopathological variables which are currently used as important diagnostic features in prostate cancer, such as stage of disease, PSA level, and Gleason Score." (PMID 27619158, 2016). "In addition, we demonstrate that IL-33 down-regulation is significantly associated with reduced survival time in human prostate cancer (97 months compared to 56.7 months)." (PMID 27619158, 2016). "In this mini-review, we compared the roles of IL-1β and IL-36 with those of IL-33 and IL-38 in prostate cancer (PCa)." (PMID 40607441, 2025). "We previously demonstrated correlation of IL-33 protein expression level with the biochemical recurrence of the human prostate tumors, which represent different stages of the human prostate cancer." (PMID 38524132, 2024). "A high number of ILC2s have been detected mainly in IL-33-enriched tumors, such as breast, gastric and prostate cancer, since IL-33 is the main ILC2s activator and usually promotes tumor growth, metastases and angiogenesis." (PMID 33233582, 2020). "Elevated numbers of ILC2s have been found in many IL-33-enriched tumors, such as breast, gastric and prostate cancer as IL-33 is an ILC2 activator that can promote tumor growth, metastatic dissemination and angiogenesis." (PMID 31849977, 2019). "Next, we evaluated the protein expression of IL-33 by immunohistochemistry in 342 prostate cancer specimens obtained at prostatectomy." (PMID 27619158, 2016). "To begin to address this question, we examined the expression of IL-33 in prostate cancer specimens obtained at the Vancouver Prostate Centre (VPC)." (PMID 27619158, 2016). "Our clinical study on human prostate tumors demonstrates the direct correlation between eosinophilic infiltration and IL-33-expression, suggesting the contribution of the IL-33/ILC2 axis to anti-tumor immune responses at earlier stages of human prostate carcinoma." (PMID 38524132, 2024). "Finally, we find corollaries of the IL-33/ILC2 axis enhancing the infiltration of eosinophils in human prostate carcinomas patients' expressing high levels of IL-33 versus those expressing low levels of IL-33." (PMID 38524132, 2024). "Interestingly, prostate cancer patients with higher IL-33 expression had a prolonged recurrence time of 97 months as compared to 56.7 months in patients with lower IL-33." (PMID 30205617, 2018). "In human prostate cancer, MHC-I/HLA and IL-33 are co-ordinately down-regulated during the metastatic re-programming of primary tumours revealing the involvement of the IL-33 gene in tumorigenesis and immune-escape." (PMID 27619158, 2016).
Splenomegaly (9 papers, 2012 to 2025). Abnormal increased size of the spleen. "Here, we expand on the mechanism by which IL33 can cause splenomegaly and the implication of this on gastric immune responses." (PMID 28210674, 2015). "Analysis of IkkeK38A/K38ATbk1fl/D135NCx3cr1-Crewt/tgIl1.18.33r-/- revealed that combined IL-1R1, IL-18R1 and IL-33R deficiency ameliorated splenomegaly, granulocytosis, and monocytosis, revealing an important role for IL-1, IL-18, and IL-33 in driving systemic inflammation in these animals." (PMID 38167258, 2024). "Indeed, Tir8/Sigirr-deficient mice showed hyper responsiveness to IL-33 with increased serum levels of IL-5 and IL-13, splenomegaly, lung inflammation, and exacerbated Th2 responses in OVA-induced allergic pulmonary inflammation." (PMID 23112799, 2012). "In spite of the lack of colonic inflammation in the WT groups, however, splenomegaly was clearly evident in both IL-10−/− and WT mice after IL-33 treatment." (PMID 24491821, 2014).
uveitis (9 papers, 2014 to 2024). An inflammatory process affecting a part of or the entire uvea. "In patients with Behçet’s disease-associated uveitis, elevated serum levels of IL-33 and IL-31 have been reported, with IL-33 playing a role in the progression of experimental autoimmune uveitis (EAU)." (PMID 39519064, 2024). "Serum levels of IL-33 have been found higher in eosinophilic granulomatosis patients with polyangiitis and Behçet disease patients with uveitis at relapse than that at the onset or during remission." (PMID 36569840, 2022). "Among those genes, a few are already known to be implicated in uveitis, such as E and P selectins, CD44, IL-33 and Lcn2." (PMID 32183784, 2020). "Our results therefore demonstrate that the endogenous IL-33/ST2 pathway plays an important role in EAU, and suggest that IL-33 represents a potential option for treatment of uveitis." (PMID 25116404, 2014). "In an experimental uveitis model, IL33 attenuated the development of the disease." (PMID 36291747, 2022). "Together our results demonstrate that IL-33 is an endogenous regulator of retinal inflammatory disease and suggest that IL-33 may be a novel therapeutic agent for uveitis." (PMID 25116404, 2014). "Recently, emerging studies are indicating that IL-33/ST2 is also involved in a wide range of ocular diseases, such as allergic eye disease, keratitis and corneal regeneration, dry eye disease, uveitis, vitreoretinal diseases, and neuromyelitis optica spectrum disorder." (PMID 32908451, 2020). "In patients with Behçet's uveitis, serum IL-33 level was significantly higher compared to patients without uveitis." (PMID 32908451, 2020). "But, although IL33 and IL31 are increased in serum of uveitis patients with Behçet’s disease and IL33 has been described to play a role in the course of EAU, the exact impact of the IL33/IL31 interplay on neutrophils in autoimmune uveitis is still unknown and merits further investigations." (PMID 36076947, 2022). "Accumulating studies have demonstrated that IL33/ST2 plays critical roles in several eye diseases, including allergic eye disease, keratitis and corneal regeneration, dry eye disease (DED), uveitis, vitreoretinal diseases, and neuromyelitis optica spectrum disorder (NMOSD)." (PMID 32908451, 2020). "Data presented here that IL-33 plays an endogenous tissue protective role in EAU and IL-33 administration ameliorates EAU, suggest that IL-33 may be a potential option for treating clinical uveitis." (PMID 25116404, 2014). "Future investigations could be taken to reevaluate the role of IL-33/ST2 among more kinds of uveitis, compare the difference between infectious versus noninfectious uveitis, or granulomatous versus nongranulomatous uveitis, and clarify potential reasons for the discrepancy." (PMID 32908451, 2020).
viral hepatitis (9 papers, 2013 to 2025). An acute or chronic inflammation of the liver parenchyma caused by viruses. "We next studied the effect of depletion of endogenous IL-33 on L2-MHV3 mediated viral hepatitis by using IL-33-deficient mice (IL-33 KO)." (PMID 28607531, 2017). "Recently, we demonstrated that the expression of IL-33 was strongly induced in the nuclei of hepatocytes in a model of viral acute hepatitis induced by the pathogenic mouse hepatitis virus L2-MHV3." (PMID 28607531, 2017). "However, there is a paucity of data regarding endogenous IL-33 deficiency on immunomodulatory effect in viral hepatitis." (PMID 28607531, 2017). "Therefore, while IL-33 plays a protective role in other models such as viral hepatitis, it has a pathogenic role in endotheliotropic diseases." (PMID 26943125, 2016). "Similar findings of IL-33-mediated protection from liver inflammation were also shown in a model of acute viral hepatitis by adeno-(Ad) infection." (PMID 30999584, 2019). "In conclusion, we demonstrated that endogenous IL-33 had multifaceted immunoregulatory effect during viral hepatitis via induction of IFNγ, survival effect on immune cells, and infiltration of neutrophils in the liver." (PMID 28607531, 2017). "Although, the IL-33 levels increased in sera of viral hepatitis patients in human, the cellular sources of IL-33 in viral hepatitis remained obscure." (PMID 24058536, 2013). "We demonstrated the cellular expression of IL-33 in sinusoidal and vascular endothelial cells and hepatocytes at various times of the fulminant viral hepatitis induced by L2-MHV3." (PMID 24058536, 2013). "The alarmin IL-33 has been described to be upregulated in human and murine viral hepatitis." (PMID 28607531, 2017). "However, the role of endogenous IL-33 in viral hepatitis remains obscure." (PMID 28607531, 2017). "Here, infecting wild-type (WT) and IL-33-deficient mice (IL-33 KO) with L2-MHV3, we showed that the alarmin IL-33 ameliorated the L2-MHV3-mediated liver injury through the regulation of IFNγ expression, survival effect on immune cells, and neutrophil infiltration in viral hepatitis." (PMID 28607531, 2017). "Furthermore, elevated IL-33 serum level was also associated with liver damage in patients of chronic hepatitis C virus (HCV) and hepatitis B virus (HBV) infections, representing IL-33 as a possible indicator of viral hepatitis." (PMID 24058536, 2013). "Albeit it is well documented that IL-33-elicited Tregs play a critical role in the regulation of liver inflammation, their contribution in viral hepatitis was not further investigated." (PMID 30999584, 2019).
vitiligo (9 papers, 2017 to 2025). Generalized well circumscribed patches of leukoderma that are generally distributed over symmetric body locations and is due to autoimmune destruction of melanocytes. "As both necroptosis and pyroptosis are lytic forms of cell death, they result in the uncontrolled release of inflammatory mediators such as high-mobility group box 1 (HMGB1), interleukin-33 (IL-33), and S100 alarmin proteins—all of which have been reported as markers associated with vitiligo." (PMID 41007740, 2025). "The serum concentrations of IL-1α and IL-33 were reported higher in vitiligo patients than that in healthy subjects." (PMID 36569840, 2022). "IL-33 and ST2 expression were both increased in lesional skin, with serum IL-33 levels increased in patients with vitiligo." (PMID 36154894, 2022). "IL-33 serum levels are more elevated in vitiligo patients than in controls." (PMID 34768860, 2021). "In patients with vitiligo, IL-33 is transferred from the nucleus to the cytoplasm in keratinocytes." (PMID 34768860, 2021). "In vitiligo, IL-33 may be considered an alarmin; it may be released by apoptotic or necrotic keratinocytes and inhibits melanocytes growth, blocking growth factors and increasing pro-inflammatory IL-6 and TNFα expression." (PMID 34768860, 2021). "Among them, a lot of genes have been described to be involved in vitiligo, such as CXCL9, CCR6, and IL-33." (PMID 35406685, 2022). "In lesions of patients with vitiligo, both ST2 and IL-33 levels were increased, and serum levels of IL-33 were increased." (PMID 28484466, 2017). "Increased expressions of IL-33 and ST2 have been observed in skin lesions of vitiligo patients." (PMID 32719716, 2020). "Therefore, in this study we would like to detect the serum expression of these alarmins (HMGB1, S100B, IL-1α, IL-33, S100A9, and S100A12) in NSV patients and healthy controls, to further investigate their clinical significance in the diagnosis and assessment of disease activity/severity in vitiligo." (PMID 36569840, 2022).
acute GVHD (8 papers, 2017 to 2023). "Our data suggest these changes contribute to acute GVHD by augmented IL-33 availability in PDPN+CD31– FRCs that then increase donor Th1 responses." (PMID 35503257, 2022). "And does IL-33 play an important role in late acute GVHD by strengthening T cell receptor signaling when a small number of minor histocompatibility antigens in the host stimulate donor T cells several months following HCT?" (PMID 35703182, 2022). "Our findings identify IL-33 as a highly desirable therapeutic target at the time of alloHCT for preventing acute GVHD." (PMID 35503257, 2022). "Inflammatory mediators, such as interleukin-33, interleukin-1β, type 1 helper T cell cytokines (interferon-γ, interleukin-2, TNF), and reactive oxygen species, were also correlated with acute GVHD." (PMID 35905125, 2022). "Differential expression analysis showed that low levels of IL18-R1, LIF-R and IL22-RA1 were seen in patients who subsequently developed acute graft versus host disease (AGvHD) whilst lower levels of CD244, TSLP, IL15-RA and IL-33 were observed in patients who developed chronic GvHD." (PMID 38235129, 2023). "IL‐33 mediates the expansion of ST2+FOXP3+ Tregs via activation of p38 MAPK signaling after HSCT, which could protect against acute GVHD." (PMID 35474948, 2022). "Soluble ST2 acts as a decoy receptor for interleukin-33 and drives T helper 2 cells toward a type 1 helper T cell phenotype, which may be important in the pathophysiology of GVHD.It is arguable that ST2 monitoring in AHSCT might identify these patients and prevent them from developing acute GVHD." (PMID 32927932, 2021).
acute respiratory distress syndrome (8 papers, 2019 to 2025). Progressive and life-threatening pulmonary distress in the absence of an underlying pulmonary condition, usually following major trauma or surgery. "The secretion of IL-33 in acute respiratory distress syndrome (ARDS) is associated with worse outcomes." (PMID 39877099, 2025). "In studies of acute respiratory distress syndrome (ARDS), IL-33 has been shown to play a critical role in modulating post-injury inflammation by controlling local cytokine levels and populations of Foxp3+ Tregs." (PMID 39301028, 2024). "The soluble form of ST2, as a down-regulation mechanism of IL-33, has been identified as a reliable biomarker of poor prognosis in cardiovascular disease, acute respiratory distress syndrome (ARDS) and other inflammatory conditions." (PMID 35327516, 2022). "Moreover, the same positive correlation was noticed regarding radiological severity, as IL-33 levels were higher among patients presenting with pulmonary multifocal consolidation and acute respiratory distress syndrome (ARDS)." (PMID 35327516, 2022).
autoimmune pancreatitis (8 papers, 2018 to 2025). "Besides, activation of plasmacytoid dendritic cells (pDCs) producing IFN-α and IL-33 plays a pivotal role in the chronic fibro-inflammatory responses underlying murine autoimmune pancreatitis (AIP) and human IgG4-related AIP." (PMID 30405626, 2018). "An imbalance of gut microbes is capable of inducing an increase in interferon-alfa (IFN-α) and interleukin 33 (IL-33) production by plasmacytoid dendritic cells and of triggering autoimmune pancreatitis." (PMID 37763780, 2023). "Gut dysbiosis was found to mediate experimental autoimmune pancreatitis (AIP) by activating pDCs, subsequently producing large amounts of IFN-α and IL-33." (PMID 37317214, 2023).
biliary atresia (8 papers, 2014 to 2025). A rare, biliary tract disease characterized by progressive obliterative cholangiopathy of the intra- and extrahepatic bile ducts, occurring in the embryonic/ perinatal period, leading to severe and persistent neonatal jaundice and acholic stool. "Furthermore, these results agree with an independent study that showed the association between IL-33 overexpression with γ-GT in biliary atresia." (PMID 35056005, 2022). "In this respect, silencing Pigr alleviated symptoms, reduced IL-33 expression and restrained hepatic Th2 inflammation in a biliary atresia mouse model." (PMID 40624587, 2025). "IL-33 can trigger cholangiocyte proliferation in a mouse model of biliary atresia, and type 2 ILCs (ILC2s) and ILC2-secreted IL-13 were found downstream of IL-33 in this mitogenic effect, which was abolished in the absence of ILC2s." (PMID 35432349, 2022). "Expression levels of Il33 mRNA are correlated with numbers of replicating cholangiocytes in an experimentally induced mouse model of biliary atresia." (PMID 26549942, 2015). "Serum IL-33 levels are elevated in patients with biliary atresia." (PMID 26549942, 2015).